HIF1A (hypoxia inducible factor 1 subunit alpha)
Diseases named in the same sentence as HIF1A in open-access papers (continued):
Sharing a sentence is not in itself a finding about the gene and the disease.
glioma (536 papers, 2007 to 2026). A benign or malignant brain and spinal cord tumor that arises from glial cells (astrocytes, oligodendrocytes, ependymal cells). "The PPI showed that VEGFA and XBP1 are key genes linked to HIF-1α and that co-expression affected glioma prognosis." (PMID 40621799, 2025). "Recent studies show that HIF-1α, a novel oncogene, is closely associated with the development and progression of glioma and predicts patient prognosis." (PMID 38734702, 2024). "Conversely, IDH-mutation gliomas have been shown to exhibit decreased activation of hypoxia-inducible factor 1α (HIF-1α), leading to a reduction in hypoxia-induced angiogenesis." (PMID 39525622, 2024). "Recent studies have shown that hypoxia inducible factor-1α (HIF-1α) were overexpressed in high-grade glioma tissues and were significantly associated with poor survival." (PMID 38734702, 2024). "High expression of METTL8 in GBM is attributed to histone variant H2AZ-mediated chromatin accessibility of HIF1α and portends inferior glioma patient outcome." (PMID 38744809, 2024). "HIF1α is overexpressed in high-grade glioma tissues and is significantly associated with poor survival." (PMID 38786726, 2024). "They reported that high HIF-1α expression in glioma was associated with increased T-cell exhaustion-related genes and immune cell numbers." (PMID 39202223, 2024). "In glioma stem cells, enhanced activity of this population was observed under hypoxic conditions; additionally, suppression of HIF-1α and HIF-2α by shRNA caused a decline in the activity of CSCs." (PMID 37328876, 2023). "The aim of present study was to elucidate the role of expression deregulations of mitochondrial sirtuin genes and co-expression with their associated proteins (SOD1, SOD2, OGG1-2α, PARP1, GDH and HIF1α) in glioma." (PMID 36809279, 2023). "For example, it has been described in glioma cells that HIF-1α activity decrease, possibly caused by a CMA-driven pathway, is related to tumour responsiveness to Temozolomide (TMZ)." (PMID 37407979, 2023). "Previous research has revealed that IDH-mutated gliomas can reduce the activation of HIF-1α, leading to the inhibition of angiogenesis and related signals." (PMID 36290819, 2022). "The presence of this mutation in glioma upregulates HIF-1a expression, which decreases c-MYC activity, resulting in a consequential decline in miR-20a, is responsible for glioma cell proliferation and resistance to temozolomide (TMZ) treatment." (PMID 36321132, 2022). "The present study is aimed therefore at clarifying the underlying mechanism of HIF-1α promoted glioma growth in vivo and in vitro by enhancing the 14-3-3β expression, which activates the downstream PI3K pathway." (PMID 35607406, 2022). "It has been reported that D-2HG competitively inhibits PHDs due to its structural similarity to α-KG, thereby causing accumulation of HIF-1α in IDH1-mutant glioma cells." (PMID 35198082, 2022). "Studies have shown IDH mutations compromise the activity of PhD and stabilize HIF-1α in glioma cells under normoxic conditions, leading to inappropriate activation of its target genes." (PMID 35198082, 2022). "Our previous study has shown that Cav-1 and HIF-1α play important roles in the progress of glioma, and both of them are significantly associated with glioma prognosis." (PMID 34287575, 2021). "For these reasons, HIF-1α has been implicated in glioma resistance to treatments due to its role in the inhibition of cell apoptosis and in the promotion of mechanisms that finally support cell survival." (PMID 33672324, 2021). "We investigated the association between HIF1A and T-cell exhaustion-related genes and immune cells in different grades of glioma and in recurrent glioma." (PMID 34305618, 2021). "Among them, HIF-1α, one of the factors associated with glioma malignancy, can be also degraded by CMA." (PMID 33672324, 2021).
glioma (continued). "Initially, IDH1 mutated glioma cells have been reported to produce lower amounts of α-KG in favor of D-2-HG, leading to HIF-1α overexpression." (PMID 34073734, 2021). "In glioma murine model, the combination treatment with HIF-1α inhibitor and anti-PD-L1 antibody caused a more pronounced suppressive effect on tumor growth compared to either monotherapy." (PMID 34118979, 2021). "The expression level of HIF-1α is significantly associated with poor survival in patients with high-grade (III+IV) gliomas." (PMID 34571995, 2021). "CircDENND2A derived from the DENND2A gene is highly expressed in HIF1α-associated glioma cells and facilitates tumor cell aggressiveness by competitive binding to miR-625-5p." (PMID 34745938, 2021). "In glioma patients, HIF-1α and PD-L1 were overexpressed in high grade glioma tissues and were significantly associated with poor survival." (PMID 34118979, 2021). "We reported CooP homing to different intracranial animal models of glioma including the murine astrocyte-derived Hif-1α-deficient (HIFko) glioma." (PMID 33918106, 2021). "Third, Pearson’s correlation analysis showed a positive association between the expressions of CAIX and HIF-1α in patients with glioma." (PMID 32823915, 2020). "In this study, an analysis of clinical relevance indicated that the levels of HIF1α were positively associated with WHO grades in 180 glioma cases, which was consistent with previous reports." (PMID 30988674, 2019). "Hypoxia is an almost universal hallmark of solid tumors, including glioma, and the HIF1α signal pathway plays an important role in cell response to the hypoxic environment." (PMID 30082910, 2019). "Clinical analysis suggested the existence of a circDENND2A/miR-625-5p axis in glioma tissues, which was associated with HIF1a." (PMID 30988674, 2019). "HIF1α importance in glioma is highlighted by the fact that mutations in IDH1/2 can lead to accumulation of HIF1α, however the most recent report states otherwise." (PMID 30510501, 2018). "Treatment with a VEGF monoclonal antibody has resulted in hearing improvement in patients with NF2-associated VS6, and delivery of siRNA against VEGF or HIF-1α to downregulate VEGF expression reduced glioma growth." (PMID 29018206, 2017). "The HIF-1α transcriptional factor and its mediated pathways are held as the principal cause for glioma malignancy and subsequent therapeutic failure." (PMID 29097800, 2017). "Overexpression of HIF-1α together with several hypoxia-related proteins, and both up- and down-stream targets of HIF-1α, have been shown to be associated with a high grade of glioma and poor survival outcome." (PMID 29097800, 2017). "Reduced migratory capacitiy of HIF-1α-deficient cells has been shown for a wide variety of primary and transformed cells, for example, neutrophils, macrophages, glioma and small cell lung cancer cells." (PMID 19223895, 2009). "The findings suggest that HIF-1α expression may be associated with the development and progression of both glial tumors and meningiomas." (PMID 40512281, 2025). "Moreover, the risk of glioma development was 31.81-fold greater, with HIF-1α serum levels exceeding the cutoff threshold." (PMID 40512281, 2025). "On the other hand, IDH mutations may favor glioma development, growth, and invasion via HIF1α induction by inhibiting PHDs." (PMID 38786726, 2024). "Tumors arise from gene mutations, and IDH1 mutations are glioma-specific, and the mutations are capable of causing HIF-1α overexpression, which may be important for the development of gliomas." (PMID 38734702, 2024). "Moreover, high HIF-1α expression associates with poor prognosis of gliomas, as well as the advanced pathological grade, 1p19q codeletion and IDH mutation status." (PMID 38678297, 2024). "High HIF1A is associated with a poor prognosis for glioma patients." (PMID 37988165, 2023).
glioma (continued). "However, HIF1α also exerts tumor suppressive effects in glial cells, and (R)-2HG has been shown to stimulate HIF1α degradation as part of the oncogenic program associated with IDH mutations in glioma." (PMID 37051530, 2023). "Besides causing metabolic shifts in glioma cells, tumoral HIF-1α stabilization also triggers pro-convulsive alterations in the surrounding tissue." (PMID 38026690, 2023). "In addition, HIF-1α was associated with the tumor angiogenesis and progression of glioma by regulating the apoptosis-related protein expression through the PTEN/Akt pathway." (PMID 35607406, 2022). "The upregulation of miRNA-199a-3p in exosomes of glioma cells induced by peritumoral hypoxia and HIF-1α activation might be the core molecular mechanism underlying the aggravated hypoxic injury of peritumoral neurons." (PMID 33110474, 2020). "A detailed study of comparative gene profiles in T cells responding to gliomas demonstrated that T cells with a higher level of Hif-1α expression were found to be closely linked to a more exhausted profile, while T cells that had a lower Hif-1α expression maintained an effector profile." (PMID 39559353, 2024). "In IDH-wildtype gliomas, this appearance may be associated with inhomogeneous growth and the upregulation of hypoxia-inducible factor 1 subunit alpha and vascular endothelial growth factor, which were associated with angiogenesis within contrast-enhancement regions." (PMID 39594235, 2024). "Moreover, hypoxic effects induced by glioma and associated with the HIF-1a factor may have a significant impact on epileptogenesis, potentially resulting in epileptiform activity within neuronal networks." (PMID 38067243, 2023). "Thus, the current study is designed to investigate expression level of SIRT3, SIRT4, SIRT5 and associated genes SOD1, SOD2, OGG1-2α, PARP1, GDH and HIF1α in glioma patients and to find out whether this expressional deregulation effects the risk of glioma." (PMID 36809279, 2023). "As cells that adapt to hypoxia tend to upregulate and stabilize HIF, it was found that expression of genes related to T-cell exhaustion is highly associated with HIF1A expression in glioma patients, indicating that HIF1A may also signal the responding hypoxia to regulate T-cell exhaustion status." (PMID 35281061, 2022). "Therefore, targeting HIF-1α and its associated regulators and gene targets in glioma could lead to benefits for cancer patients." (PMID 31530290, 2019). "HIF-1α expression affects glioma tumor growth, which suggests clinical applications in treating malignant gliomas." (PMID 40429943, 2025). "Elevated HIF-1α levels in the glioma microenvironment are known to contribute to increased P2X7R expression, since hypoxic conditions increase extracellular ATP levels, and P2X7R is activated exclusively in high-ATP environments." (PMID 41034696, 2025). "Previous studies indicate that overexpression of PAX6 markedly reduces the protein level of hypoxia inducible factor-1α (HIF-1α) in glioma cells." (PMID 41154694, 2025). "The necrotic glioma microenvironment which is exacerbated by neuroinflammation, generates a hypoxic environment where the ability of glioma cells to adapt and thrive is mediated by HIF-1α, which is upregulated in glioblastoma." (PMID 41034696, 2025). "In U87, LN229, and C6 glioma cells, pVHL overexpression results in the reduction in HIF-1α, VEGF, and Bcl-2 as well as enhanced apoptosis, G0/G1 cell cycle arrest, reduced tumor growth, and invasion." (PMID 41155273, 2025). "Silencing HIF-1α with siRNA in the G55 glioma cell line reversed this hypoxia-induced suppression of GOT1 and GOT2 expression." (PMID 39914740, 2025). "In a study conducted by Reszec and colleagues, HIF-1α expression was evaluated in 154 meningioma cases of different grades and 106 glial tumors, including 24 diffuse astrocytomas, 40 anaplastic astrocytomas and 42 GBMs." (PMID 40512281, 2025).
glioma (continued). "The HIF1α expression increases gradually with the increase of the grade of glioma and in GBM patients whose tumours reoccurred after treatment." (PMID 41007296, 2025). "A comparison of concentrations within the same glioma grades in plasma samples and homogenates showed statistically significant differences in the case of HIF-1α in grades G2 and G4, for ANG-2 in grade G1, and for IL-1β in grades G2 and G4." (PMID 40429943, 2025). "Our analysis revealed a positive correlation between HIF-1α and CD47 gene expression in gliomas, with an associated correlation coefficient of 0.22." (PMID 39781344, 2025). "HDL was used as a nanoplatform for the co-delivery of a fluorescent dye and a small interfering RNA (siRNA) for Hypoxia-inducible factor 1-alpha (HIF-1α) for enhanced photo-gene therapy towards glioma." (PMID 40574048, 2025). "In the case of high-grade gliomas, JAK1/2-STAT3 along with a hypoxia-induced pathway utilizing hypoxia-inducible factor 1α (HIF-1α) TF has been reported for enhancing the self-renewal capability of glioma stem-like cells." (PMID 40548119, 2025). "It was found that overexpression of HIF-1α enhanced glioma cell proliferation and partially rescued the growth inhibition induced by PAX6." (PMID 41154694, 2025). "These proliferation profiles align well with previous reports of reduced HIF-1α stabilization in IDH-mut gliomas and increased glycolytic adaptation in IDH-wt tumors." (PMID 40722659, 2025). "Hypoxia is common in gliomas, and as the main effector molecules of hypoxia, HIF1α and HIF2α promote the malignant progression by inhibiting cell apoptosis and maintaining stemness." (PMID 40370575, 2025). "Future prospective studies incorporating comprehensive molecular profiling will be important to validate the clinical utility of GAL-8, ITGβ-1, and HIF-1α in well-characterized glioma subtypes." (PMID 40512281, 2025). "HIF-1α overexpression in gliomas is also driven by the activation of EGFR via the PI3K pathway, with EGFR gene amplification being a demonstrated hallmark of glioblastoma that contributes to gliomagenesis." (PMID 41034696, 2025). "HIF1α and HIF2α, the main effector molecules of hypoxia, play important roles in the hypoxic microenvironment to promote the malignant progression of gliomas." (PMID 40370575, 2025). "The signaling pathways through which IGF1R, activated by HIF1α and HIF2α, promotes tumor cell proliferation and therapy resistance in glioma cells are also worth exploring." (PMID 40290443, 2025). "In this setting, glioma cells also upregulate immune checkpoint molecules such as PD-L1 in response to HIF-1α, leading to functional exhaustion of infiltrating T cells." (PMID 41583467, 2025). "The diagnostic values of serum GAL-1, GAL-8, ITGβ-1, HIF-1α, and MMP-9 as a potential biomarker for gliomas were assessed using ROC curve analysis." (PMID 40512281, 2025). "In future studies, the spatial co-localization of GAL-8 and HIF-1α at the glioma tissue level should be assessed by immunohistochemistry or multiplex imaging techniques." (PMID 40512281, 2025). "In summary, this study illustrates that PAX6 promotes ferroptosis in glioma cells by suppressing HIF-1α by regulating intracellular ROS and oxidative stress." (PMID 41154694, 2025). "tRF-22 negatively regulates MXD1 expression by binding to the 3’UTR of MXD1 mRNA, thereby diminishing MXD1’s transcriptional repression of the HIF1A gene and promoting glioma VM formation." (PMID 40140670, 2025). "Targeting HIF-1α has been the subject of clinical trials for the treatment of gliomas, with limited results." (PMID 40338274, 2025). "tRF-22 negatively regulates MXD1 expression by binding to its 3’UTR, reducing MXD1’s transcriptional inhibition of HIF1A, thereby promoting glioma cell proliferation, migration, invasion, and tube formation." (PMID 40140670, 2025). "Hypoxia or HIF-1α can promote VM formation in gliomas, lung adenocarcinoma, colorectal cancer, and other cancers." (PMID 40140670, 2025).
glioma (continued). "The proangiogenic compounds involved in the development of glioma include hypoxia-inducible factor 1α (HIF-1α), angiopoietin-2 (ANG-2), and interleukin-1β (IL-1β)." (PMID 40429943, 2025). "Immunohistochemical staining analysis of the excised tumor tissues revealed that PAX6 overexpression also markedly suppressed the expression of HIF-1α in glioma cells in vivo, consistent with the findings from in vitro experiments." (PMID 41154694, 2025). "This study reveals a novel tumor-suppressive mechanism of PAX6 in gliomas, whereby it inhibits HIF-1α to induce ferroptosis, ultimately suppressing tumor growth." (PMID 41154694, 2025). "In a subsequent study, the high MAO-B expression demonstrated a positive correlation with the tumor grade, the transcription factor Sp3 and HIF1α, the latter being localized in the nuclei in advanced gliomas or in the cytosol in low-grade gliomas." (PMID 39714760, 2025). "This study proposes that PAX6 induces (ROS) accumulation in glioma cells, which subsequently suppresses HIF-1α expression and promotes ferroptosis." (PMID 41154694, 2025). "tRF-22 negatively regulates the transcription factor MXD1 expression, diminishing its transcriptional repression of the HIF1A gene, thus promoting VM formation in gliomas." (PMID 40140670, 2025). "The CGGA database indicates that HIF1α and HIF2α are highly expressed in gliomas, with their expression levels gradually increasing with tumor grade, reaching the highest levels in glioblastoma." (PMID 40290443, 2025). "Recent bioinformatic analysis of RNA-seq data from The Cancer Genome Atlas (TCGA) and the Chinese Glioma Genome Atlas (CGGA) database revealed that both HIF-1α and HIF-2α are significantly overexpressed in GBM tumors as compared to normal brain tissue." (PMID 41155273, 2025). "In the murine glioma model, the combination of HIF-1α inhibitor with anti-PD-L1 antibodies induces a synergistic reduction in tumor growth compared with the treatments alone." (PMID 41155273, 2025). "Firstly, immunohistochemistry, qPCR, Western blot, and other methods were used to detect PAX6 and HIF-1α expression in glioma tissues and cells, as well as the specific way in which PAX6 regulates HIF-1α." (PMID 41154694, 2025). "For example, in glioma cells, HIF-1α can directly bind to the PD-L1 promoter region, enhancing PD-L1 expression." (PMID 40429910, 2025). "Tests for glioma based on the determining concentrations of HIF-1α, ANG-2, and IL-1β will indicate the presence of the disease at higher concentrations of these proteins, because the diagnostic value of each variable increases with concentration." (PMID 40429943, 2025). "In this study, we evaluated the serum levels of GAL-1, -3, and − 8, along with ITGβ-1, HIF-1α, MMP-2, and − 9, as potential diagnostic markers in glioma." (PMID 40512281, 2025). "Individuals whose serum HIF-1α concentration surpassed 1411.00 pg/mL demonstrated statistically elevated probability of developing glioma than did those with lower ones (OR: 31.81, p < 0.01)." (PMID 40512281, 2025). "Hypoxia is also a driver in PD-L1 expression, in combination with the co-expression of PD-L1 and HIF-1α in glioma cells under hypoxia." (PMID 41155273, 2025). "Supportingly, another study recorded high levels of HIF-1α expression in glioma cells than in normal human astrocytes." (PMID 40512281, 2025). "Culturing glioma cells in a stiff ECM enhances HIF1A expression, which subsequently increases the expression of tenascin C, a critical component in the aggressiveness of gliomas." (PMID 40150879, 2025). "This study confirmed that hyperbaric oxygen can inhibit ABCG2 expression through HIF1α and HIF2α, thereby promoting the proliferation and chemosensitization of gliomas." (PMID 40370575, 2025). "Hypoxia within gliomas has been shown to activate hypoxia-inducible factor 1 alpha (HIF-1α), which in turn promotes tumour neoangiogenesis by stimulating VEGF expression." (PMID 40733274, 2025).